BDNF (brain derived neurotrophic factor)
Diseases named in the same sentence as BDNF in open-access papers (continued):
Sharing a sentence is not in itself a finding about the gene and the disease.
depression (continued). "Yang and colleagues tested the role of serum BDNF in predicting depression after stroke." (PMID 33809965, 2021). "We suggested that juvenile TBI treatment may have long-term regulation effects on the hippocampal BDNF and TrkB expression, leading to increased depression-like behavior in adulthood." (PMID 34959450, 2021). "Thus, a vicious cycle has been postulated in which increased cortisol levels due to depression lead to decreased BDNF function, and pathological degeneration of AD leads to further decreased BDNF function." (PMID 34881077, 2021). "Most studies involving older adults with depression observed lower plasma or serum levels of BDNF." (PMID 33643008, 2021). "Overall, a number of previous observations as well as some more recent evidence emphasize the significance of TrkB as a valuable target for antidepressants and reaffirm the critical role of BDNF/TrkB signaling in the pathophysiology of depression and in antidepressants action." (PMID 34948177, 2021). "Another study reported that inhibited function of the CREB1/BDNF/NTRK2 pathway had a negative impact on the risk mechanism of depression." (PMID 34333859, 2021). "Notably, BDNF as a clue to explore potential biomarkers of cardiovascular diseases comorbid depression has been reported." (PMID 34163381, 2021). "Rodents subjected to more intense maternal separation exhibited more significant behavior changes in anxiety, depression and contextual fear memory, correlated with more diminished BDNF mRNA and protein levels, decreased H3K9 acetylation and increased HDAC2 levels in the hippocampus." (PMID 34744641, 2021). "CRMH also reversed the decrease in hippocampal BDNF levels caused by corticosterone, suggesting the CRMH may be effective in chronic stress-related depression." (PMID 34360959, 2021). "Moreover, infusion of BDNF recombinant protein or a TrkB agonist into the CA3 hippocampus promoted long-lasting antidepressant effects in mice models of depression." (PMID 34565419, 2021). "One possible factor triggering depression is the involvement of brain-derived neurotrophic factor (BDNF) mediating significant atrophy and structural changes in the brain, as part of the BDNF-hypothesis of depression." (PMID 34577589, 2021). "Moreover, CC2D1A/Freud-1 can affect BDNF function thereby possibly playing a substantial part in the pathogenesis of various mental disorders, including depression." (PMID 34948116, 2021). "In this study, we investigated whether the ratio of serum BDNF level and depression scale of HAMD-24, or NI, was useful for prediction of the long-term antidepressant outcome, using Yueju and/or escitalopram in two trials." (PMID 34776888, 2021). "Further findings—that the blood levels of BDNF were found to be reduced not only in psoriasis but also in depression, and thus may link major depression with psoriasis—call for studies to also integrate BDNF into psycho-dermatology." (PMID 34685457, 2021). "Although the functional significance of this BDNF induced potentiation remains to be investigated in future, it is likely that BDNF may contribute to chronic pain, emotional anxiety, fear, or depression in the ACC." (PMID 34526080, 2021). "Decreased BDNF levels in the brain tissues of depressed patients may be associated with the decreased plasticity of neurons in the central nervous system, and decreased serum BDNF will lead to a depression-like state." (PMID 34046258, 2021). "Unlike mature BDNF, proBDNF has been linked with the promotion of long-term depression and cell death." (PMID 34071762, 2021). "From a biochemical perspective, a persistent state of oxidative stress leads to low BDNF levels, increasing the vulnerability to depression symptoms, which could be treated by improving antioxidant defenses." (PMID 34769814, 2021). "The disruption of BDNF and TrkB homeostasis is involved in the pathophysiology of depression." (PMID 34451801, 2021).
depression (continued). "A prevailing view in the field is that ketamine restores the functional integrity of neural circuits that are compromised in depression through a synaptogenic process that is triggered by the rapid activity-dependent release of brain-derived neurotrophic factor (BDNF)." (PMID 34772915, 2021). "Novel observations led to the “neurotrophic hypothesis of depression”, highlighting the functional significance of alterations in neurotrophic factors, particularly the brain-derived neurotrophic factor (BDNF)." (PMID 34325733, 2021). "As alterations in BDNF levels directly affect the pathogenesis of depression, the regulation of these levels might lead to the development of treatments for depression." (PMID 34577589, 2021). "In addition, other studies have shown that BDNF plays an important role in the pathogenesis of severe depression." (PMID 33833815, 2021). "Plasminogen activator inhibitor-1 (PAI-1) could act as a mediator of depression-induced CVDs through sleep disorder, adiposity, BDNF metabolism, systemic inflammation, and hypothalamic-pituitary-adrenal (HPA) axis dysregulation." (PMID 34163381, 2021). "Importantly, while impaired hippocampal neurogenesis can lead to depression, studies have demonstrated that the upregulation of BDNF levels stimulate hippocampal neurogenesis." (PMID 34068707, 2021). "In addition, BDNF favors regulation of brain plasticity in neural networks, which play important roles in depression." (PMID 34161531, 2021). "The results suggest that the NI may represent an individual’s trait that links BDNF with depression symptom, and early change of NI may predict long-term antidepressant efficacy." (PMID 34776888, 2021). "A similar study has shown that Vit D can increase the BDNF level in UCMS depression model." (PMID 34381124, 2021). "Exogenous BDNF has antidepressant effect in the animal model of depression." (PMID 33833815, 2021). "The neuroplasticity hypothesis of depression is supported by the evidence of decreased concentration of brain-derived neurotrophic factor (BDNF) in both animal models of depression and patients with depression." (PMID 34645783, 2021). "A clinical study showed increased BDNF protein levels in the NAc in patients with depression." (PMID 34577589, 2021). "Our study found that the depression score was negatively correlated with BDNF." (PMID 34046258, 2021). "Long-term sleep deprivation may lead to sleep disturbance and depression while reducing BDNF levels." (PMID 34093193, 2021). "Moreover, the infusion of BDNF into the hippocampus has been shown to improve depression-like behaviors in rats, suggesting that BDNF has antidepressant effects in vivo." (PMID 35155523, 2021). "Importantly, the distinct alteration of BDNF expression in brain regions of rodents is involved in LPS-induced depression." (PMID 34207497, 2021). "The expression of BDNF in the amygdala might be an intervention target in patients with comorbid alcoholism and depression, and BDNF thus has therapeutic potential for drug addiction and various mental diseases." (PMID 33919862, 2021). "At the end of this study, we concluded that taVNS could improve depression symptoms and sleep quality in alcohol-dependent patients after withdrawal, which might be related to the upregulation of plasma BDNF levels." (PMID 34526917, 2021). "In addition, regular exercise promotes the release of several trophic factors, including brain-derived neurotrophic factor (BDNF), which exerts a positive role in both anxiety and depressive disorders." (PMID 33572883, 2021). "The neurotrophic factor hypothesis of depressive disorder suggests that antidepressant therapy plays a role by increasing the expression of BDNF in the brain, enhancing prominent plasticity and promoting the survival of neurons." (PMID 34207545, 2021). "Previous studies have suggested a link between BDNF and depressive disorders." (PMID 34576215, 2021).
depression (continued). "The authors of that research emphasized that BDNF val66met polymorphism did not directly influence ones’ vulnerability to depressive disorders, but that its occurrence was more probable following stressful events." (PMID 34573321, 2021). "For this reason, the authors suggested that BDNF may play different roles in depressive disorders between the sexes." (PMID 34576215, 2021). "In a meta-analysis, patients with depressive disorder showed increased BDNF levels after ECT." (PMID 34576215, 2021). "In addition, changes in BDNF levels were noted in patients with depressive disorder after appropriate treatment." (PMID 34576215, 2021). "In addition, we considered that the neurotrophic factors, such as brain-derived neurotrophic factor (BDNF), connect the treatment of depression disorder with changes in cortical thickness." (PMID 35273524, 2021). "Both male and female adolescents with depressive disorder showed lower BDNF levels than HCs." (PMID 34576215, 2021). "The hypothesis that BDNF replenishment mediates antidepressant effects supports the role of BDNF in depressive disorders, as BDNF was found to possibly play a role in the therapeutic mechanism of antidepressants." (PMID 34876186, 2021). "It is established that BDNF could be involved in behavioral phenomena connected with depressive disorders as well as antidepressant treatment effectiveness." (PMID 33804455, 2021). "The antidepressant properties of DISS and TFSA can be attributed to their ability to influence 5‐HT and BDNF pathway, and thereby suggesting that this combination strategy can definitely act as alternative therapy for depression disorder with very limited side effects." (PMID 33598202, 2021). "Another research suggested that BDNF in plasma is mainly stored in platelets and their release is correlated with each other, as a result, there is a correlation between serum BDNF levels with serotonin and depression." (PMID 32085720, 2020). "Therefore, acupuncture promoted synaptic plasticity via BDNF protein expression and regulated a few miRNAs that were found to target BDNF, which seem to play important roles in the development of depression." (PMID 33029119, 2020). "As BDNF plays a critical role in the therapeutic process of depression, the increase in the hippocampal BDNF levels may be an important therapeutic molecular mechanism underlying the antidepressant activity of SOCG." (PMID 33224257, 2020). "Recent findings have reported that BDNF is a key regulator in the neuro-immune axis regulation, but its potential mechanism in depression remains unclear." (PMID 33213019, 2020). "Moreover, following chronic unpredictable mild stress, rats showed depression-like behaviors and decreased BDNF and increased miR-182 in the hippocampus." (PMID 32085670, 2020). "In conclusion, these results indicate that BDNF is an important biomarker of depression and may exert antidepressant effects by activating ERK and CREB." (PMID 32185198, 2020). "While BDNF decreases in depression, exercise tends to increase the level of BDNF in the brain, which may bring about an amelioration of depressive symptoms similar to the effects of antidepressant treatment." (PMID 33154698, 2020). "Moreover, in a bulbectomy rat model of depression, ingestion of FO increased the hippocampal level of brain-derived neurotrophic factor (BDNF) and 5HT, which are the two major regulators of neuronal survival and long-term plasticity in the brain." (PMID 33066310, 2020). "Depression also increases the level of inflammatory factors in the hippocampus, downregulates BDNF, and impairs synaptic plasticity, all of which contribute to the development and long-term pathophysiology of depression." (PMID 33552119, 2020).
depression (continued). "Met/ Met genotype of the BDNF has a higher probability of depression than others." (PMID 32281722, 2020). "BDNF regulates the growth and maintenance of the neuronal system as well as neuronal plasticity, like long-term potentiation of learning, which has been shown to be reduced in major depressive disorders." (PMID 33353117, 2020). "BDNF is also known to be related to mental symptoms, such as depression and anxiety." (PMID 32859253, 2020). "Furthermore, BDNF/TrkB signaling plays a key role in the pathophysiology of depression and has been found to be a therapeutic target for antidepressant drugs." (PMID 33109198, 2020). "The results showed 83 new BDNF gene SNPs, six of which were related to depression." (PMID 32351365, 2020). "In addition, BDNF demonstrates neuroprotective effects in a CORT-induced model of depression in female mice." (PMID 32570881, 2020). "The BDNF-TrkB signaling pathway may further activate transcription factors to mediate the comorbidity of addiction and depression." (PMID 32694984, 2020). "Related reports have found that CSS can significantly improve the depression status of model rats, and its mechanism may be related to the increase of mRNA expression of BDNF and TrkB in the hippocampus, amygdala, and frontal lobe." (PMID 32185198, 2020). "One of them may be the brain-derived neurotrophic factor (BDNF) which is negatively correlated with depression and its level is also lower in rheumatoid arthritis." (PMID 32977410, 2020). "The serum BDNF level was significantly positively correlated with the abundance of the Lachnospiraceae family (Lachnospiraceae_uc and Murimonas) and was negatively correlated with OCTT_g (Ruminococcaceae) abundance in those with depression." (PMID 32570775, 2020). "However, results are still inconclusive, as high blood BDNF levels were revealed also in resistant depression subjects under pharmacological treatment." (PMID 32517269, 2020). "Physical rehabilitation may be impaired by depressions, and depressed patients are less likely to exercise what lowers the level of BDNF and intensify functional impairment." (PMID 33213019, 2020). "A recent study showed that alterations in inflammatory cytokines and BDNF might contribute to neuropathic pain-induced depression." (PMID 29882089, 2020). "The relationships between BDNF and depression may be more complex and involve gene-environment interactions or the duration of depression." (PMID 33233633, 2020). "Secondly, stress could reduce the level of brain-derived neurotrophic factor in major depressive patients." (PMID 32580488, 2020). "Altered BDNF levels have been found in patients with depression and its co-morbidities." (PMID 33233416, 2020). "Depression reportedly increases the negative regulation of ERK signaling associated with synaptic plasticity and inhibits downstream signaling of BDNF and neuritin that are essential for normal synaptic function." (PMID 32922295, 2020). "Structurally similar as resveratrol, Pterostilbene isolated from the Chinese herbal medicine Dragon’s blood can promote the development of adult rat neurogenesis, up-regulate BDNF (brain-derived neurotrophic factor, BDNF) and alleviate depression-like behaviors." (PMID 32982748, 2020). "MS stress can increase sensitivity to neuropathic pain on inducing depression-like behaviors only in female mice, but not in males, which is associated with differential BDNF expression in the hippocampus and striatum between the two sexes." (PMID 32085670, 2020). "BDNF is probably the most studied of them as one of its specific variants (Val66Met, G to A, rs6265) has been consistently reported to influence the predisposition to CVD associated with depression." (PMID 33233416, 2020). "As reported, exercise could induced the increased level of brain-derived neurotrophic factor (BDNF), which contributed the increased ability against anxiety and depression in mice." (PMID 33329133, 2020).
depression (continued). "The excessive secretion of adrenal hormones and proinflammatory cytokines accelerates the occurrence of anxiety/depression by suppressing brain-derived neurotrophic factor (BDNF) expression in the brain, gut inflammation and dysbiosis by activating innate and adaptive immunities in the intestine." (PMID 32224881, 2020). "Hence, Stress events compromise neuroplasticity via reduction of BDNF and lead to the occurrence of depression." (PMID 33658934, 2020). "However, there was limited reporting of the effects of multicomponent exercise on depression and brain-derived neurotrophic factor for this group of people." (PMID 32191630, 2020). "While BDNF plays a role in serotonergic expression, it may also itself be regulated by 5-HT, particularly in depression and stress." (PMID 33584798, 2020). "BDNF expression in brain is known to increase in subjects treated with antidepressants compared with antidepressant-untreated subjects, and BDNF levels were significantly lower in patients of major depression." (PMID 32181410, 2020). "In conclusion, ECS has the ability to increase the levels of BDNF, though depression may mitigate against increases in BDNF." (PMID 32153449, 2020). "Changes in BDNF levels are marked in neuropsychiatric disorders, in particular, depression." (PMID 33152026, 2020). "While the available antidepressants such as fluoxetine and venlafaxine are known to elevate the levels of NGF and BDNF both in the serum of depression patients and in depression-like animal models, the long-term use of these antidepressants can cause many side effects." (PMID 33364963, 2020). "Interestingly, when controlling for pre-displacement exposures, higher levels of BDNF and NGF were associated with worse scores on validated scales for PTSD, depression, and anxiety." (PMID 32142533, 2020). "So BDNF may have different effects on depression-like behavior in the different brain areas and neuron networks (Castrén and Rantamäki, 2010a,b; Castrén and Kojima, 2017)." (PMID 32351365, 2020). "BDNF has an effect on regeneration and increases hippocampus functions, and a decrease in BDNF has been found to be related to depression in the elderly, suggesting that exercise may be able to reverse and prevent depressive symptoms by increasing BDNF25." (PMID 33106570, 2020). "Sufficient BDNF content regulates synaptic plasticity and participates in reversing depression." (PMID 32266752, 2020). "BDNF plays an important role in the development of depression and antidepressant treatments." (PMID 32307916, 2020). "Several evidence strongly suggest that altered BDNF signaling may be related to the pathogenesis of several neurological disorders including Huntington's disease, Alzheimer's disease, and depression." (PMID 31951637, 2020). "In addition to the reduction of BDNF in the presence of stress and depression symptoms, it was observed that the expression levels of pro- and anti-inflammatory cytokines in brain tissue were also regulated." (PMID 33256231, 2020). "In the present study, we investigated the effects of EA on tPA/BDNF pathway-related molecules in the hippocampus and raphe nuclei to better understand its mechanisms in the treatment of depression, thereby helping provide a theoretical basis for the clinical application of EA." (PMID 32153441, 2020). "BDNF, a member of the neurotrophin family, plays critical roles in cell differentiation, neuronal survival, migration, and synaptic plasticity and has been suggested to be involved in the pathogenesis of depression." (PMID 33256231, 2020). "Similar to depression, the decreased BDNF level is a vulnerability factor for anxiety." (PMID 33329133, 2020). "BDNF and CREB have been reported to be involved in neuronal differentiation and survival, as well as in synaptic plasticity associated with learning and memory in various nervous system disorders, including depression." (PMID 32754030, 2020).